GATA6 (GATA binding protein 6)
Diseases named in the same sentence as GATA6 in open-access papers (continued):
Sharing a sentence is not in itself a finding about the gene and the disease.
pancreatic cancer (continued). "Our findings indicate that GATA6 amplification and overexpression contribute to the oncogenic phenotypes of pancreatic cancer cells, and identify GATA6 as a candidate lineage-specific oncogene in pancreatobiliary cancer, with implications for novel treatment strategies." (PMID 18535672, 2008). "To directly assess the functional significance of GATA6 amplification and overexpression in pancreatic cancer, we used RNA interference (RNAi) to target GATA6 knockdown in two pancreatic cancer cell lines, AsPC1 and Panc3.27, with GATA6 gain and overexpression." (PMID 18535672, 2008). "These authors concluded that the presence of LINC00261 and GATA6 may impair the self-renewal and tumorigenesis capacity of pancreatic cancer stem cells, whereas the suppression of ITIH5 expression caused by LINC00261 downregulation rescued these tumorigenic functions." (PMID 35158755, 2022). "Mechanistically, loss of EP300 directly downregulated GATA6 expression, thereby silencing the GATA6-regulated differentiation program and leading to a phenotypic transition from the classical subtype to the dedifferentiated basal-like/squamous subtype of pancreatic cancer." (PMID 35536676, 2022). "Notably, given that the frequency of genetic alterations in EP300 is less than 2% in treatment-naive pancreatic tumors, there are likely to be additional mechanisms regulating GATA6 expression in basal-like tumors that may be dependent or independent of p300." (PMID 35536676, 2022). "Interestingly, in digestive system cancers, such as esophageal adenocarcinoma, pancreatic cancer, colorectal cancer or cholangiocarcinoma, GATA6 could be used as a prognostic tumor marker for different mechanisms." (PMID 30872657, 2019). "However, PDACs also exhibited a high incidence of amplification or gain of GATA4 and GATA6, suggesting that in certain instances these TFs may confer a growth advantage to pancreatic cancer cells." (PMID 30190481, 2018). "In summary, the present review emphasizes the roles of some microRNAs, GATA6, L1CAM, and MUC1 in pancreatic cancer." (PMID 40699746, 2025). "This review aims to discuss the new functions of important biomarkers, such as miRNAs, GATA6, L1CAM, and MUC1 in pancreatic cancer." (PMID 40699746, 2025). "Upregulation of GATA6 enhanced chemosensitivity of pancreatic cancer cells, and KRAS/ERK inhibitors synergized with chemotherapy in a GATA6-dependent manner." (PMID 41329526, 2025). "With regards to GATA6, its miRNA-mediated knockdown in SW1990 pancreatic cancer cells inhibits cell proliferation, enhances ROS generation, and promotes cell death via apoptosis." (PMID 39456519, 2024). "In our study, we discovered a link between the expression of SOX9 in pancreatic cancer cell lines and the expression of the GATA4 and GATA6 proteins." (PMID 35884771, 2022). "In pancreatic cancer stem cells, the long non-coding RNA (lncRNA) LINC00261 was suggested to bind to GATA6, increasing its activity at the ITIH5 promoter." (PMID 35158755, 2022). "GATA6 has been shown to induce EMT in breast cancer cells, however it was found to suppress EMT in pancreatic cancer cells." (PMID 34708244, 2022). "A previous study showed a direct influence of GATA6 on DKK1 and thus on Wnt regulation in pancreatic carcinoma." (PMID 32075129, 2020). "In pancreatic cancer, differential hydroxymethylation of genes related to pancreas development or function (GATA4, GATA6, PROX1, ONECUT1, MEIS2), and cancer pathogenesis (YAP1, TEAD1, PROX1, IGF1) have also been shown to reliably identify pancreatic cancer from peripheral blood samples." (PMID 36835649, 2023). "Moreover, their subsequent work revealed that GATA6 regulated EMT and tumor dissemination of pancreatic cancer." (PMID 32596145, 2020).
pancreatic cancer (continued). "Regarding the potential target(s) of GATA6 that might be crucial in stimulating CRCSCs, liver receptor homolog‐1 (LRH‐1) is of particular interest because this transcription factor has been reported to play a role in CSC stemness and EMT in pancreatic cancer." (PMID 32037723, 2020). "Similarly, immunolabeling for GATA6 in five pancreatic cancers with copy number gain showed strong positive nuclear labeling whereas no labeling was seen in five pancreatic cancers with copy numbers <2.3." (PMID 21811562, 2011). "In complementary experiments, we attempted to overexpress GATA6 by retroviral transduction in nontumorigenic human pancreatic ductal epithelial HPDE cells, and in the pancreatic cancer cell line PL45 harboring activated KRAS but no 18q11.2 gain." (PMID 18535672, 2008). "In contrast, siRNA transfection of a pancreatic cancer cell line, PL45, without GATA6 amplification and overexpression did not diminish cell proliferation, supporting the specificity of GATA6 targeting." (PMID 18535672, 2008).
gastric cancer (31 papers, 2014 to 2026). A primary or metastatic malignant neoplasm involving the stomach. "Suppression of GATA6 in gastric cancer is associated with poor prognosis and likely promotes tumorigenesis by reducing the expression of trefoil factor 1 (TFF1) and trefoil factor 2 (TFF2)." (PMID 29720137, 2018). "Higher GATA6 expression levels have been associated with favorable prognosis in gastric cancer." (PMID 41152570, 2026). "Methylation of GATA6 may be able to serve as an early diagnostic marker in gastric cancer." (PMID 27598141, 2016). "GATA6 also acts as an oncoprotein in gastric cancer, colorectal cancer, breast cancer, and cutaneous T-cell lymphoma whereby it promotes tumor progression." (PMID 40416104, 2025). "There were 1,107 genes showing hypomethylation in AGS/shSTAT3 cells, as compared to control (AGS/shGFP), including GATA6 in which its promoter methylation has already been confirmed in AGS gastric cancer cells and patients samples in our previous study." (PMID 33718136, 2021). "For example, miR-143 targets GATA6 to inhibit cell proliferation in gastric cancer cell lines and exert tumor suppression effects." (PMID 34946965, 2021). "Hypermethylation of the GATA6 promoter was observed in the epigenetic signatures of glioblastoma 36 and gastric cancer." (PMID 33859766, 2021). "Abnormal GATA2 epigenetic dysregulation can induce unfavorable phenotypes in human gastric cancer by decreasing expression of GATA6, which has a vital role in gastrointestinal development." (PMID 34539736, 2021). "It has been reported that aberrant DNA methylation on GATA2 affects GATA6 expression levels in gastric cancer progression." (PMID 33579350, 2021). "For example, GATA6 suppresses gastric cancer cell migration and metastasis via the miR-520b-mediated repression of CREB1." (PMID 33659248, 2021). "In this study, we employed an untargeted metabolomics based on UPLC Q-Exactive Focus mass spectrometry to investigate metabolic pathways of GATA6 regulating trastuzumab resistance in gastric cancer cells." (PMID 33173435, 2020). "The present study showed that GATA6 knockout resulted in the down-regulation of ME2 in trastuzumab resistant gastric cancer cells, which in turn reduced ATP production and ultimately inhibited the proliferation of cells." (PMID 33173435, 2020). "Our previous studies demonstrated that the activity of GATA6 binding protein 6 (GATA6) enhanced prominently in trastuzumab resistant gastric cancer cell lines (NCI N87R and MKN45R)." (PMID 33173435, 2020). "Despite all of this, metabolic pathways and characteristics of GATA6 regulating trastuzumab resistance have yet to be elucidated in gastric cancer." (PMID 33173435, 2020). "Our study showed that GOT1 and GOT2 were decreased in trastuzumab resistant gastric cancer cells with GATA6 knockout, suggesting that GATA6 maintains basal expression of GOT1 and GOT2." (PMID 33173435, 2020). "Recent studies have shown an influence on the cell cycle in gastric carcinoma, where a depletion of GATA6 led to a cycle arrest in the M-phase and thus to significantly slower tumor growth." (PMID 32075129, 2020). "GATA6 has also been shown to operate in gastric cancer, and recent genome sequencing data indicated that CIN variant gastric, GOJ, and EAC tumors are closely related at the molecular level." (PMID 30962179, 2019). "Our results demonstrate that there is an inverse relationship between the expression of STAT3 and GATA6 in gastric cancer patients." (PMID 27598141, 2016). "This study also demonstrated that GATA6 is epigenetically silenced by promoter methylation in patients with gastric cancer." (PMID 27598141, 2016). "The expression of GATA6 was correlated with promoter methylation in all gastric cancer cell lines except for SNU1 and GES cells." (PMID 27598141, 2016). "Results from RNA sequencing identified an inverse correlation between the expression of STAT3 and GATA6 in 23 pairs of gastric cancer patient samples." (PMID 27598141, 2016).
gastric cancer (continued). "In this study, we found that the expression level of GATA6 is inversely correlated with that of STAT3 in gastric cancer patients." (PMID 27598141, 2016). "We are therefore the first to report that GATA6 can be epigenetically silenced by promoter methylation in gastric cancer." (PMID 27598141, 2016). "We discovered that the expression of GATA6 is epigenetically silenced through promoter methylation in gastric cancer cell lines." (PMID 27598141, 2016). "Additionally, there are reports from gastric cancer that suggested multiple roles of GATA6 within carcinogenesis." (PMID 33300112, 2021). "Recovering the abnormal metabolism of GATA6 in gastric cancer cells could be a potential therapeutic strategy for dealing with trastuzumab resistance." (PMID 33173435, 2020). "Our results showed that GATA6 knockout inhibited mitochondrial functions in NCI N87R and MKN45R cells, indicating that GATA6 could be a potential therapeutic target for dealing with trastuzumab resistance in gastric cancer." (PMID 33173435, 2020). "Our data therefore imply that blocking transcriptional activity of GATA6 could be an effective strategy to attenuate trastuzumab resistance in gastric cancer." (PMID 33173435, 2020). "Taken together, these findings demonstrate that GATA6 is involved in metabolism reprogramming which might contribute to trastuzumab resistance in gastric cancer." (PMID 33173435, 2020). "We therefore hypothesized that the downregulation of GATA6 could lead to the downregulation of TFF1/2 in gastric cancer." (PMID 27598141, 2016). "Therefore, targeting the GATA6/miR-520b/CREB1 axis may be an effective approach for the treatment of gastric cancer." (PMID 33659248, 2021). "For instance, reduced GATA6 expression may inhibit gastric cancer progression." (PMID 33315534, 2021). "Thus, it might suggest that nucleotide metabolism mediated by GATA6 also contributes to trastuzumab resistance in gastric cancer cells." (PMID 33173435, 2020). "The suppression of GATA6 may further downregulate TFF1/2 in gastric cancer." (PMID 27598141, 2016). "It is noteworthy that GATA6 and CDX2 were both enriched in our DGC analysis—this combination likely reflects the intestinal-type gastric cancers that commonly arise in the distal stomach." (PMID 40862793, 2025). "GATA6 which located on chr18q11.2 locus (amplified in ITGB1 low subgroup), suppressed migration and metastasis by regulating the miR-520b/CREB1 axis in gastric cancer." (PMID 37007126, 2023). "GATA6 upregulation has been shown in several tumors in the past, including CRC, gastric cancer, and cholangiocarcinoma." (PMID 36239104, 2022). "Based on dataset GSE54129, involving 111 gastric cancer and 21 normal mucosa samples, we identified four TFs including CREB1, BPTF, GATA6 and CEBPA with high DR value among top 1% DRGs." (PMID 35421923, 2022). "This is in keeping with our finding that there is extensive overlap between the binding of KLF5 and GATA6 which is reinforced by recent studies that show that KLF5 binds with GATA6 in OAC and gastric cancer." (PMID 32880368, 2020). "Consistently, we found that GATA6 knockout resulted in decreased expression of GLS and thereupon disturbed glutamate and glutamine metabolism in trastuzumab resistant gastric cancer cells." (PMID 33173435, 2020). "Taken together, these results suggest that GATA6 contributes to trastuzumab resistance, which is dependent on TCA cycle and mitochondrial function in gastric cancer." (PMID 33173435, 2020). "Among these genes, deregulation of STAT3, GATA6, SOX2, and FOXA2 in gastric cancer was already reported previously in independent studies." (PMID 29720137, 2018).
gastric cancer (continued). "Our analysis, thus, showed that abnormal expression of BMP1, COL1A1, STAT3, GATA6, SOX2 and FOXA2 forms an ubiquitous molecular signature of gastric cancer patients in Southwestern Taiwan." (PMID 29720137, 2018). "In the current study, we observed a positive correlation between the expression of GATA6 and TFF1/2 in patients with gastric cancer and in gastric cancer cell lines." (PMID 27598141, 2016). "A clinically significant correlation was also observed between the expression of GATA6 and TFF1/2 among tissue samples from 60 gastric cancer patients." (PMID 27598141, 2016). "A significantly positive correlation was observed between the expression of GATA6 and TFF1/2 in the full set of patients with gastric cancer (n = 60)." (PMID 27598141, 2016). "Given that GATA6 is a transcription factor of the gastroprotective trefoil genes TFF1/2, we therefore examined the expression of TFF1/2 in gastric cancer cell lines." (PMID 27598141, 2016). "The family member ELF3 was well expressed in the mRNA level in a subset of gastric cancers (n = 91), and its expression correlated with the expression of other transcription factors involved in gastric cancer pathogenesis, including HNF4A, HNF1A, CDX2, GATA4, GATA6, and EHF." (PMID 41425714, 2025). "In conclusion, our study demonstrated that GATA6 is involved in TCA cycle, glycometabolism, amino acid and nucleotide metabolism, thereby leading to reprogramming in the metabolism and promoting trastuzumab resistance in gastric cancer cells." (PMID 33173435, 2020). "KLF5 is also frequently amplified in gastric cancer and has recently been shown to regulate gene expression in OAC in combination with other transcription factors, GATA6, ELF3 and EHF." (PMID 32880368, 2020). "CLRN3 has been identified as a HNF4A transcriptional target in iPSC-derived hepatocytes, and CLDN18 has been confirmed as a GATA6 target in gastric cancer; therefore, we used these likely targets to test the regulatory potential of HNF4A and GATA6 in OE19 cells." (PMID 30962179, 2019). "Importantly, treatment with 2.5 μm of RHD6 restored the expression of GATA6 and TFF1/2 in AGS, MKN28, and MKN45 gastric cancer cells." (PMID 27598141, 2016). "In the current study, gastric cancer cells were then treated with rhodium(III) complex 6 (RHD6), a novel STAT3 inhibitor, to determine whether the suppression of STAT3 would derepress GATA6 and TFF1/2." (PMID 27598141, 2016). "These distinct regulatory programs suggest that gastric cancers should not be treated as a uniform entity; rather, location-specific biomarkers like CDX2 or GATA6 could potentially inform prognosis and therapeutic decisions." (PMID 40862793, 2025).
colorectal cancer (29 papers, 2011 to 2026). A primary or metastatic malignant neoplasm that affects the colon or rectum. "GATA-6 may be an effective target of colorectal cancer cells, but in general, the region downstream of transcription factors such as GATA-6 encodes a vast protein network." (PMID 34151031, 2021). "For example, miR-944 may function as a tumor suppressor to inhibit colorectal cancer (CRC) by regulating GATA6, and their expression level was negatively associated with the pathological manifestation of CRC." (PMID 34952600, 2021). "In colorectal cancer, upregulation of miR‐196b‐5p was found to target and reduce the expression of GATA6, thereby acting as a positive regulator of the Wnt/beta‐catenin pathway in this context." (PMID 41152570, 2026). "GATA6, known to regulate differentiation in gastric and colorectal cancers, plays a defining role in PDAC subtype stratification with major prognostic implications." (PMID 41303383, 2025). "In agreement with our findings, GATA6 exhibited an oncogenic function in colorectal cancer through repression of BMP expression, contributing to invasion and metastasis through regulation of the uPA protease." (PMID 39456519, 2024). "We have reported that anisomycin potently inhibited the proliferation of colorectal cancer-derived DLD-1 cells under planar culture or spheroid culture conditions through induction of proteolysis of transcription factor GATA-6." (PMID 34151031, 2021). "We previously demonstrated that anisomycin induced the degradation of transcription factor GATA-6 in DLD-1 cells (a colorectal cancer cell line) and inhibited their proliferation." (PMID 34151031, 2021). "LncRNA Gata6 increased cancer cell stem-like properties and promoted occurrence in colorectal cancer." (PMID 31300015, 2019). "The most significant TF, GATA6, has been reported to promote colorectal cancer invasion, and its aberrant expression is correlated with poor prognosis and liver metastasis in colorectal cancer." (PMID 25648588, 2014). "In the Apc-null mouse model of colorectal cancer, GATA6 is required for tumor initiation." (PMID 32157212, 2020). "However, studies of NOX1 expression in Caco-2 human colorectal cancer cells demonstrated that binding of the transcription factor GATA6 to the NOX1 promoter played an important role in the regulation of NOX1 expression." (PMID 28498822, 2017). "The potential influence of GATA6 expression on the response to oxaliplatin treatment remains to be examined; notably, a prior study involving colorectal cancer has indicated that enhancing GATA6 protein levels might augment the resistance of colorectal cancer stem cells to oxaliplatin." (PMID 39717718, 2025). "In accordance with our results, cell migration of established colorectal cancer cell (CRC) lines is decreased upon GATA6 knockdown and enhanced by GATA6 overexpression." (PMID 36523548, 2022). "Since we previously found that GATA6 promotes the stemness in HCT‐116 and HT‐29 human colorectal cancer (CRC) cells, we aimed to identify the downstream mediator(s) of the stemness‐stimulating effect of GATA6 herein." (PMID 32037723, 2020). "For example, GATA binding protein 6 (GATA6), by regulating the expression of ALDOB, may promote fructose metabolism and liver metastasis of colorectal cancer." (PMID 39980550, 2025).
colorectal cancer (continued). "Furthermore, miR-363-3p was found to directly target and repress GATA6, which is a transcription factor enhancing the expression of LGR5 in colorectal cancer." (PMID 27816053, 2016). "Gata6 expression is up-regulated in colon cancer epithelial cells, as well as in non-malignant cells along the stromal margins in human colorectal cancer, but it should be noted that it has not been determined whether this is a correlative, causative or protective event." (PMID 24472151, 2014).